RGS8 (regulator of G protein signaling 8)
Description:
Regulates G protein-coupled receptor signaling cascades, including signaling via muscarinic acetylcholine receptor CHRM2 and dopamine receptor DRD2 (By similarity). Inhibits signal transduction by increasing the GTPase activity of G protein alpha subunits, thereby driving them into their inactive GDP-bound form. Modulates the activity of potassium channels that are activated in response to DRD2 and CHRM2 signaling (By similarity).
Synonyms: MGC119067; MGC119068; MGC119069
Tractability: Small molecule: a structure with a bound ligand is known. Antibody: its Gene Ontology location is reachable by antibodies, with high confidence; UniProt places it where antibodies can reach, with medium confidence; the Human Protein Atlas places it where antibodies can reach. PROTAC: a small molecule that binds it is known.
Target class: Enzyme
Gene: Protein-coding gene on chromosome 1 (182,641,816 to 182,684,587, reverse strand). Ensembl gene ENSG00000135824.
Subcellular location: Cell membrane; Membrane; Perikaryon; Cell projection, dendrite; Nucleus
Subcellular location (Human Protein Atlas): Plasma membrane; Vesicles
Pathways (Reactome):
Signal Transduction: G alpha (i) signalling events
Gene Ontology:
Molecular function: GTPase activator activity; protein binding; GTPase activity
Biological process: positive regulation of GTPase activity; G protein-coupled acetylcholine receptor signaling pathway; G protein-coupled receptor signaling pathway; negative regulation of G protein-coupled receptor signaling pathway; regulation of dopamine receptor signaling pathway
Cellular component: cytoplasmic side of plasma membrane; dendrite; neuronal cell body membrane; nucleus; plasma membrane; membrane; perikaryon; synapse
Genetic constraint (gnomAD): Loss-of-function variants: 4 observed, 15.8 expected, observed/expected ratio (o/e) 0.25, 90% interval 0.12 to 0.58. The upper end of that interval is the gene's LOEUF score, 0.58, which puts it in group 2 of 6, group 1 being the genes least tolerant of losing a copy. Missense variants: 134 observed, 195.3 expected, observed/expected ratio (o/e) 0.69, 90% interval 0.6 to 0.79. Synonymous variants: 70 observed, 75.72 expected, observed/expected ratio (o/e) 0.92, 90% interval 0.76 to 1.13.
Homologues: Orthologues: guinea pig RGS8 (99% identical), mouse Rgs8 (98% identical), chimpanzee RGS8 (96% identical), dog RGS8 (96% identical), macaque RGS8 (96% identical), pig RGS8 (96% identical), rat Rgs8 (94% identical), rabbit RGS8 (68% identical), tropical clawed frog rgs8 (66% identical), zebrafish rgs8 (59% identical). Paralogues in human: RGS16 (56% identical), RGS3 (51% identical), RGS4 (48% identical), RGS5 (46% identical), RGS2 (44% identical), RGS18 (43% identical), RGS1 (41% identical), RGS21 (38% identical), RGS19 (36% identical), RGS20 (35% identical), RGS13 (34% identical), RGS14 (33% identical), and 11 more.
Diseases named in the same sentence as RGS8 in open-access papers:
RGS8 is named in the same sentence as 27 diseases in open-access papers, as found by Europe PMC text mining. Sharing a sentence is not in itself a finding about the gene and the disease. The quoted sentences say what the papers report.
Ataxia (3 papers, 2020 to 2024). Ataxia refers to impaired coordination of voluntary muscle movement. "Recently, RGS8 was shown to be associated with the pathology of several forms of spinocerebellar ataxia (SCA), an inherited disease associated with cerebellar degeneration." (PMID 35712654, 2022). "In this study, we designed two crRNA targeting regulator of G-protein signaling 8 (RGS8), which is a signaling molecule associated with spinocerebellar ataxias." (PMID 35712654, 2022). "Ataxia with anti-regulator of G-protein signaling 8 autoantibodies (RGS8-Abs) is an autoimmune disease recently described in four patients." (PMID 39207522, 2024). "In the moment, little is known about the role of RGS8 for pathogenesis of spinocerebellar ataxia." (PMID 33553137, 2020). "Consequently, suspicion of RGS8-Abs ACA with lymphoma should be raised in cases of subacute cerebellar ataxia without evidence of an underlying malignancy, and patients should be evaluated accordingly." (PMID 39207522, 2024). "Interestingly, loss of RGS8 in an RGS8 null mutant mouse model goes together with normal development of Purkinje cells and the mice show no signs of ataxia." (PMID 35712654, 2022). "As in other paraneoplastic ACA with intracellular antigen, RGS8-ataxia is probably T-cell mediated and antibodies are unlikely to be pathogenic." (PMID 39207522, 2024).
thyroid cancer (3 papers, 2022 to 2024). "The mRNA and protein expression levels of regulator of G protein signalling 8 (RGS8) in normal tissues are greater than those in thyroid carcinoma tissues." (PMID 39233332, 2024). "To further investigate the significance and mechanism of RGS8, DGKI and OCA2 in thyroid cancer, we summarized the relationship between RGS8, DGKI and OCA2 expression and clinical features in the TCGA database of THCA patients." (PMID 36059514, 2022). "RGS8 has not been reported to be associated with thyroid cancer." (PMID 36059514, 2022). "To investigate the role of RGS8, DGKI and OCA2 expression, we explored the relationship between RGS8, DGKI, and OCA2 expression and clinical features in thyroid cancer patients, and the expression data were obtained from TCGA." (PMID 36059514, 2022). "Our results revealed that the expression of RGS8, DGKI, and OCA2 in thyroid carcinoma was negatively correlated with multiple types of immune cell infiltration, including dendritic cells (DCs and aDCs), macrophages and neutrophils." (PMID 36059514, 2022). "In addition, RGS8, DGKI, and OCA2 were expressed at low levels in thyroid cancer in our sequencing results, GSE33630 and GSE29265." (PMID 36059514, 2022).
encephalitis (2 papers, 2024 to 2025). An acute inflammatory process affecting the brain parenchyma. "Patients with RGS8-Abs were identified retrospectively in the biological collections of the French Reference Center for Paraneoplastic Neurological Syndrome and the University of California San Francisco Center for Encephalitis and Meningitis." (PMID 39207522, 2024).
papillary thyroid carcinoma (2 papers, 2022 to 2024). "Similar to BMP8A, there are no comprehensive studies yet that explore the relationship between RGS8 expression and the prognosis of papillary thyroid carcinoma, indicating an area ripe for further research." (PMID 38671425, 2024). "In our study, we identified three genes associated with SUMOylation modification—BMP8A, RGS8, and SERPIND1—as significant to the prognosis of papillary thyroid carcinoma (PTC) patients." (PMID 38671425, 2024). "Given the critical role of immune factors in the progression of papillary thyroid carcinoma (PTC), our study aimed to elucidate the correlations between BMP8A, RGS8, and SERPIND1 and immune cell infiltration." (PMID 38671425, 2024). "Then, we detected the protein expression of RGS8, DGKI and OCA2 in five pairs of papillary thyroid carcinoma tissues and found that their expression levels were obviously lower than those of the paired normal thyroid tissues." (PMID 36059514, 2022).
autoimmune thyroid disease (1 paper, 2022). Inflammatory disease of the thyroid gland due to autoimmune responses leading to lymphocytic infiltration of the gland. "The enrichment plots of the GSEA showed that thyroid hormone production and its peripheral downstream signalling effects, thyroxine biosynthesis, and autoimmune thyroid disease were significantly enriched in RGS8, DGKI and OCA2." (PMID 36059514, 2022). "The GSEA showed that RGS8, DGKI and OCA2 were enriched in thyroid hormone production and its peripheral downstream signal transduction effects, thyroxine biosynthesis, and autoimmune thyroid diseases." (PMID 36059514, 2022).
Autoimmunity (1 paper, 2024). The occurrence of an immune reaction against the organism's own cells or tissues. "The present study found a strong expression of the RGS8 antigen specifically in the scattered popcorn cells, but not in the microenvironment, only in patients with RGS8-Abs, which highlights a potential link between the lymphomagenesis and anti-RGS8 autoimmunity." (PMID 39207522, 2024).
B-cell lymphoma (1 paper, 2024). "Hence, regarding the current diagnostic criteria, RGS8-Ab are at least Abs of intermediate risk of PNS, with a preferential association with B-cell lymphoma, particularly HL." (PMID 39207522, 2024). "Among the seven identified patients with RGS8-Abs, the tumor identification was available for four, and all of them presented with a B-cell lymphoma; one with a diffuse large B-cell lymphoma of the stomach and three with an HL (one from the previous published study and two herein)." (PMID 39207522, 2024).
breast carcinoma (1 paper, 2022). "RGS8 has been reported in human breast cancer and pancreatic cancer, and was downregulated in ovarian cancer, but the molecular mechanism remains unclear." (PMID 36059514, 2022).
breast tumors (1 paper, 2010). "To test the calculation strategy, three probes were designed to cover regions in Regulator of G-protein Signaling 8 (RGS8), which we previously have identified as being affected by allelic imbalance by LOH analysis across RGS8 in the cohort comprising 145 breast tumors." (PMID 20579386, 2010). "The same issue might concern the set of synthetic probes designed to validate previously identified allelic imbalances within the RGS8 in breast tumor samples." (PMID 20579386, 2010).
depression (1 paper, 2021). "As related to depression, the RGS family members, RGS2, RGS4, RGS6 and RGS8 have all surfaced as being involved with regulating the manifestation of depression or play role as antidepressants through their capacity to activate different downstream molecular mechanisms." (PMID 34674723, 2021).
diabetes (1 paper, 2022). "RGS16 and RGS8 are expressed in embryonic pancreatic progenitor and endocrine cells and disappear in adults; however they are reactivated in type I and II diabetes models, which suggests that the RGS16 and RGS8 proteins may become a novel target for further treatment of diabetes." (PMID 36120550, 2022).
hearing loss (1 paper, 2025). "Then, to further investigate whether RGS8 and ORC1 play a role in age-related hearing loss, we verified the expression of RGS8 and ORC1 in spiral ganglion neurons from different ages of mice." (PMID 40617800, 2025).
Insulin resistance (1 paper, 2022). Increased resistance towards insulin, that is, diminished effectiveness of insulin in reducing blood glucose levels. "Finally, the associations of RGS8, RGS13, RGS18, and RGS21 with insulin secretion or insulin resistance need to be further investigated." (PMID 36497154, 2022).
lymphoma (1 paper, 2024). A malignant (clonal) proliferation of B- lymphocytes or T- lymphocytes which involves the lymph nodes, bone marrow and/or extranodal sites. "Autoantibodies detected in all patients enriched the same epitope on the RGS8 protein, which is an intracellular protein physiologically expressed in Purkinje cells but also ectopically expressed specifically in lymphoma cells of patients with RGS8-related ACA." (PMID 39207522, 2024). "In this respect, it would be especially interesting to screen lymphoma patients without neurological symptoms for anti-RGS8 antibodies to determine the antibodies’ specificity." (PMID 39207522, 2024).
spinocerebellar ataxia type 1 (1 paper, 2020). Spinocerebellar ataxia type 1 (SCA1) is a subtype of type I autosomal dominant cerebellar ataxia (ADCA type I) characterized by dysarthria, writing difficulties, limb ataxia, and commonly nystagmus and saccadic abnormalities. "Evidences were provided that increased miR-150 levels found in Purkinje neurons of the mouse model of spinocerebellar ataxia type 1 may modulate disease pathogenesis by targeting the expression of RGS8 and VEGFA genes." (PMID 32655365, 2020).
synucleinopathy (1 paper, 2024). A neurodegenerative disease that is characterized by the abnormal accumulation of aggregates of alpha-synuclein protein in neurons, nerve fibers or glial cells. "In the present analysis, both Drd2 and Rgs8 transcripts decrease in early synucleinopathy." (PMID 38172128, 2024).
cancer (3 papers, 2022 to 2024). A tumor composed of atypical neoplastic, often pleomorphic cells that invade other tissues. "While various RGS family members have been implicated in malignant tumor development, information on RGS8 remains scarce." (PMID 38671425, 2024). "As described in other cancer associated with PNS, this strong expression of RGS8 only in the tumor cells of patients with PNS may be the trigger of the immune cross-reaction, and can thus be responsible for the death of Purkinje cells in which RGS8 is physiologically expressed." (PMID 39207522, 2024). "The present study aimed to identify other patients with RGS8-Abs, describe their clinical features, including the link between RGS8-related autoimmune cerebellar ataxia (ACA) and cancer." (PMID 39207522, 2024). "First, using TISIDB, we analysed the relationship between the expression levels of RGS8, DGKI and OCA2 and the level of immune cell infiltration in different cancers." (PMID 36059514, 2022). "We first evaluated RGS8, DGKI, and OCA2 expression across cancers." (PMID 36059514, 2022).
tumor (3 papers, 2022 to 2024). "RGS8-Abs are directed against an intracellular antigen specifically expressed in the tumor cells, the popcorn cells, NLPHL’s hallmark, and physiologically expressed in the Purkinje cells, which are targeted by the autoimmune reaction." (PMID 39207522, 2024). "IHC staining revealed RGS8 cytoplasmic strong expression specifically in the “popcorn cell” of the tumor samples of both patients." (PMID 39207522, 2024). "By quantifying ssGSEA in the THCA tumor environment, we applied the Spearman correlation to prove the correlation between the level of immune cell infiltration and the expression of RGS8, DGKI and OCA2." (PMID 36059514, 2022). "Fluorescent in situ hybridization (FISH) was performed to assess the variation of copy number of RGS8 but results were inconclusive because of the rarity of tumor cells (representing less than 1% of the cells) scattered in the inflammatory environment (data not shown)." (PMID 39207522, 2024). "Similarly, by analysing RGS8, DGKI, and OCA2 expression in the TCGA database, we found that their expression in 58 THCA tumor samples was lower than that in 58 paired normal samples." (PMID 36059514, 2022). "Therefore, it can be inferred that downregulation of BMP8A, RGS8, and SERPIND1 might lead to a shift in the immune microenvironment towards a pro-tumor state, thus facilitating the occurrence and advancement of PTC." (PMID 38671425, 2024). "Then, we used qRT–PCR and a Western blot analysis to detect the expression of RGS8, DGKI and OCA2 in tumor tissues and corresponding noncancer tissues from THCA patients." (PMID 36059514, 2022).
cardiovascular disease (1 paper, 2014). "The 155 - 157 Mb interval is syntenic with Chr1q25, where an intron SNP marker in RGS8 is associated with cardiovascular disease (8.9) and SNPs near and within the CACNA1E gene are associated with HDL cholesterol levels (9.5), echocardiography (5.2) and blood pressures (4.9)." (PMID 24586312, 2014).
RGS8 also shares sentences with these, for which no sentence is quoted: autoimmune disease (1 paper); cerebellar ataxia (1); Hodgkins lymphoma (1); Huntington disease (1); meningitis (1); ovarian carcinoma (1); pancreatic cancer (1); paraneoplastic neurological syndrome (1).